ORAI1 (ORAI calcium release-activated calcium modulator 1)
Diseases named in the same sentence as ORAI1 in open-access papers (continued):
Sharing a sentence is not in itself a finding about the gene and the disease.
breast cancer (continued). "Interestingly, it has recently been shown that STIM1 regulates breast cancer cell migration through NFAT1 signaling independent of Orai1 and SOCE in breast cancer cells." (PMID 38505262, 2024). "Hence, we have further explored the specific functional role of Orai1 glycosylation in SOCE in non-tumoral breast epithelial cells and breast cancer cells." (PMID 36612199, 2022). "Moreover, silencing ORAI1, but not STIM1, sensitizes MDA-MB-231 basal breast cancer cells to staurosporine-induced apoptosis." (PMID 35682546, 2022). "Expression of the ORAI1 Ca2+ influx channel is higher in breast cancers of the basal molecular subtype, which are often triple‐negative (i.e., do not express estrogen, progesterone, and HER2 receptors) compared to nonbasal breast cancers." (PMID 31647602, 2020). "In breast cancer cells, Feng and colleagues have demonstrated that SPCA2 (Secretory Pathway Ca2+-ATPase 2) is able to interact with and activate Orai1, triggering a calcium entry that does not depend on Stim1 and intracellular calcium stores’ depletion and sustaining cells proliferation." (PMID 30718673, 2019). "Till now, though not as much as those reported in breast cancer cells and osteoclasts, multiple calcium channels have also been reported to modulate osteoblast proliferation, differentiation, migration and mineralization, including TRPV1, TRPV4, TRPM7, TRPP2, Cav1.2, ORAI1/SOCE, P2X1, and P2X7." (PMID 32211326, 2020). "Conversely, no functional role has so far been established for Stim1 and Orai1 paralogues, that is, Stim2 and Orai2, in carcinogenesis, while Orai3 is recruited by Stim1 to activate SOCE and cell proliferation in some oestrogen receptor-negative human breast cancer lines." (PMID 25126575, 2014). "Studies identifying the carboxyl terminal of SPCA2 as an activator of ORAI1 and the interaction between SPCA2 and ORAI1 in MCF-7 breast cancer cells, suggests that the up regulation of SPCA2 may not only serve to promote Ca2+ secretion during lactation, but also as an activator of Ca2+ influx." (PMID 24359162, 2013). "Therefore, the non-stimulated Ca2+ influx observed in MDA-MB-468 breast cancer cells, which is sensitive to both TRPC1 and ORAI1 knockdown, may be due to enhanced ER Ca2+ leak through TRPC1, the consequence of which is increased store-regulated Ca2+ influx through ORAI1." (PMID 22666335, 2012).
Immunodeficiency (47 papers, 2012 to 2026). Failure of the immune system to protect the body adequately from infection, due to the absence or insufficiency of some component process or substance. "Mutations in human Orai1 cause severe immunodeficiencies and myopathies, yet structural insights have remained largely elusive." (PMID 42113836, 2026). "The patient’s clinical presentation as CRAC channelopathy with immunodeficiency is likely explained by several aspects of his H134P and L194P mutations in ORAI1." (PMID 41200103, 2025). "Important insight into the function of STIM and Orai1 proteins has been gleaned from studies on patients suffering from immunodeficiencies with loss-of-function (LoF) mutations in these genes." (PMID 40459545, 2025). "Biallelic sequence variants in ORAI1 are also associated with infections in severe combined immunodeficiency due to impaired T cell activation, and a case of ORAI1 deficiency presented with immunodeficiency and residual T cell function." (PMID 41473684, 2025). "In lymphocytes in particular, Orai1 has been considered as essential, as patients with mutations in Orai1 display a SCID-like immunodeficiency." (PMID 38534312, 2024). "Patients with inherited loss-of-function (LoF) mutations in Orai1 (e.g. R91W mutation) develop a CRAC channelopathy with symptoms including combined immunodeficiency, ectodermal dysplasia, muscular hypotonia, and autoimmunity." (PMID 36803766, 2023). "Accordingly, patients carrying homozygous ORAI1 LoF mutations abolishing SOCE manifest immunodeficiency associated with skin anomalies, ectodermal dysplasia, and muscular hypotonia, emphasizing the importance of operative SOCE for normal development." (PMID 35805973, 2022). "The most prominent example for the essential role of Orai1 in the immune system is exemplified by a single point mutant (Orai1 R91W), leading to severe combined immune deficiency." (PMID 34360783, 2021). "Human studies have revealed that loss-of-function Orai1 mutations cause severe immunodeficiencies and defects in muscle function frequently resulting in death in the first year of life, highlighting the vital importance of Orai1 channels for human health." (PMID 33264616, 2020). "Patients with an Orai1 mutation (R91W) show muscular hypotonia along with severe combined immunodeficiency (SCID), mainly due to depressed SOCE." (PMID 32244622, 2020). "Orai1 mutations cause human immunodeficiency, resulting in chronic and often lethal infections, while Orai1-knockout mice die at around the time of birth." (PMID 32447449, 2020). "Loss-of function mutations in Orai1 Ca2+ channels lead to a form of severe combined immunodeficiency, auto-immunity, muscle hypotonia and defects in dental enamel production and sweat gland function." (PMID 31600783, 2020). "Another mutation R429C, which is situated in STIM1 C-terminus, impairs coupling to Orai1 and has been connected to combined immune deficiencies." (PMID 33333945, 2020). "Mutations in human STIM1 and Orai1 have been found in patients with immunodeficiency, highlighting the importance of SOCE in T cell activation." (PMID 28240257, 2017). "Recently, a point mutation in the Orai1 gene at the R91W locus was discovered to be associated with a severe immunodeficiency in patients." (PMID 22787461, 2012). "Mutations in STIM1 and Orai1 genes are clinically characterized by severe immunodeficiency and congenital myopathy in human patients." (PMID 22984609, 2012). "Here, we show that a unique H134P mutation in ORAI1 is associated with immunodeficiency and HLH." (PMID 41200103, 2025). "Moreover, ORAI1-deficient patients have dental enamel defects and anhidrosis, representing a new form of anhidrotic ectodermal dysplasia with immunodeficiency." (PMID 39873967, 2025).
Immunodeficiency (continued). "While patients and mouse models with loss of function (LoF) mutations in Orai1 present with severe immunodeficiency due to impaired T cell function, the development of most immune cell populations is largely unaltered, suggesting SOCE is dispensable for initial immune cell selection and development." (PMID 36803766, 2023). "Furthermore, homozygous variants within PRKDC and ORAI1 genes have already been associated with immune dysfunction, such as severe forms of immunodeficiency and autoimmunity." (PMID 36294757, 2022). "The main reported clinical manifestation of the ORAI1 loss-of-function mutations in patients is immunodeficiency resulting from impaired T cell activation and cytokine production, which highlights the fundamental role of ORAI1 in immune response against pathogens." (PMID 35113933, 2022). "Mutations within ORAI1 originally manifested as severe combined immune deficiency (SCID)." (PMID 35113933, 2022). "Hence, Orai1 is critical in a multitude of cellular processes, as apparent from a variety of gain-of-function (GoF) and loss-of-function (LoF) mutations within Orai1 that have been linked to diseases such as severe combined immune deficiency." (PMID 34360783, 2021). "Patients with mutations in Orai1 manifest skeletal myopathies and immunodeficiencies, for example." (PMID 32244622, 2020). "Indeed, Orai1-knockout mice die at around the time of birth, and Orai1 mutations in humans cause immunodeficiency, leading to chronic infections that are often lethal, and various non-immunological symptoms." (PMID 32447449, 2020). "Loss-of-function mutation of ORAI1 caused immune deficiency and dysfunction of thrombus formation." (PMID 32799904, 2020). "It was reported that mutations of either ORAI1 or STIM genes lead to channelopathy-dependent immunodeficiency, which conceivably could be at least in part due to reduced T cell proliferation and cytokine secretion depending on decreased calpain activation." (PMID 27835610, 2016). "Given the polygenic nature of immune diseases such as RA, the susceptibility gene ORAI1 could provide new clues to the pathogenesis of RA." (PMID 24808640, 2014). "Mutations in STIM1 and ORAI1, the genes that encode the functional channel, are tightly linked to a CRAC channelopathy in humans, which encompasses severe combined immune deficiency, myopathy and anhidrotic ectodermal dysplasia." (PMID 40459545, 2025). "Loss-of-function variants in STIM1 and ORAI1 cause calcium release-activated channelopathies (CRAC) with ectodermal dysplasia, leading to enamel defects and anhidrosis, immunodeficiency, and muscular hypotonia with muscle weakness." (PMID 39804930, 2025). "STIM1-ORAI1 coupling is required for the proliferation of T cells, and patients bearing loss-of-function mutations in STIM1 or ORAI1 suffer from severe combined immunodeficiencies." (PMID 40116769, 2025). "These defects are reminiscent of the attenuated T cell function reported in other ORAI1- and STIM1-deficient patients and likely contribute to the patient’s severe immunodeficiency." (PMID 41200103, 2025). "Loss-of-function mutations of ORAI1 suppress store-operated Ca2+ entry (SOCE) and cause an immunodeficiency disorder called Ca2+ release–activated Ca2+ channelopathy." (PMID 41200103, 2025). "Recessive, loss-of-function mutations in STIM1 or ORAI1 result in reduced protein expression or disrupted STIM1-ORAI1 coupling, thus leading to insufficient SOCE and severe combined immunodeficiency." (PMID 39420094, 2024). "Orai1 R91W, Orai1 G98R, and Orai1 A103E, all located in TM1, are LoF mutations that cause immunodeficiencies." (PMID 33430308, 2021). "ORAI1 and K+ channels (Kv1.3 and KCa3.1), extensively expressed in T-lymphocytes, are crucial targets in the treatment of a variety of immune diseases." (PMID 34639190, 2021).
Immunodeficiency (continued). "The revealed missense ORAI1 mutation is associated with defective SOCE and ICRAC, resulting in loss of fine control of Ca2+-mediated processes characterized by a severe immunodeficiency with myopathy." (PMID 33117812, 2020). "We next tested P11 efficacy on two lymphoblastoid cell lines (“LCL”) established from an Orai1-deficient with a severe combined immunodeficiency (“LCL Orai1−”) and a healthy (“LCL Orai1+”) patients." (PMID 33371518, 2020). "ORAI1, a gene related to cellular immune system, has been shown to be involved in the pathogenesis of chronic inflammatory diseases and immune diseases." (PMID 24808640, 2014). "This is evidenced by phenotype observations in patients or animal models with abnormal ORAI1 or STIM1 expression, which shows compromised CD4+ and CD8+ T cell functions related with humoral and cellular immunity, ultimately leading to immunodeficiencies and susceptibility to severe infections." (PMID 38791278, 2024). "Recessive STIM1 and ORAI1 loss-of-function (LoF) mutations inhibit SOCE and Ca2+ store refill and cause immunodeficiency (IMD9 and IMD10, OMIM # 612782, #612783), characterized by recurrent and chronic infections, autoimmunity, muscular hypotonia, mydriasis, and amelogenesis imperfecta." (PMID 35805973, 2022). "The recessive Orai1 LoF mutations in TM1, R91W, G98R, and A103E, are linked to immunodeficiencies." (PMID 33333945, 2020). "Consequently, there has been considerable interest in identifying Orai1 modulators, excluding immune diseases, as therapeutics for more conditions." (PMID 33117812, 2020). "These phenotypes in immune cells of Stim1- and Orai1-deficient mice are consistent with those of the severe combined immunodeficiency (SCID) symptoms found in human patients who have mutations in the Stim1 or Orai1 gene, resulting in abnormal STIM1 or Orai1 functions." (PMID 30340324, 2018). "Although abolished SOCE, T cell dysfunction and immunodeficiency in these patients indicate that ORAI1 is the dominant CRAC channel subunit in human effector T cells, these findings do not exclude a potential role of ORAI2 in other immune or non-immune cells in which it is expressed." (PMID 28294127, 2017). "Alterations in STIM1/Orai1 system may contribute to several pathophysiological conditions including cardiovascular and pulmonary diseases, hypertension, immunodeficiency, and autoimmune and lymphoproliferative diseases." (PMID 26064953, 2015). "The patient’s immunodeficiency and his other non–immune-related symptoms including thermoregulatory instability (indicative of anhidrosis) and muscular hypotonia are consistent with CRAC channelopathy disease reported in other patients with LOF mutations in ORAI1 and STIM1 genes." (PMID 41200103, 2025). "The importance of Orai1 for lymphocyte function appears from the fact that the protein was identified after the discovery of a point mutation creating a non-functional channel, inducing a severe combined immunodeficiency." (PMID 33371518, 2020). "The immunodeficiency observed in the absence of Orai1 has made this protein a promising drug target to treat diseases caused by an over-active immune system, such as autoimmune and inflammatory diseases." (PMID 32447449, 2020). "In humans, the lack of function of Orai1 is dominated clinically by immunodeficiency with mostly normal overall T, B, and NK cell counts." (PMID 33117812, 2020). "The absence of a functional Orai1 essentially induces a severe combinated immunodeficiency, without affecting other major organ functions." (PMID 31320998, 2019). "This missense mutation in Orai1 did not interfere with interactions between Orai1 and STIM1, which suggest that the immunodeficiency is derived from defective Orai1 driven Ca2+ flux." (PMID 22787461, 2012).
prostate carcinoma (44 papers, 2012 to 2024). A carcinoma that arises from epithelial cells of the prostate gland. "On the other hand, in prostate cancer cells Orai3 expression has been associated with the formation of Orai1/Orai3 heteromeric channels regulated by AA and reduction in SOCE, thus leading to enhanced proliferation." (PMID 34768857, 2021). "This selective utilization of Orai3 by prostate cancer cells can partially be attributed to greater evasion of apoptotic signals closely associated with sole Orai1 functioning." (PMID 32599788, 2020). "In prostate cancer, it was suggested that ORAI1 is implicated in a dynamic machinery of Ca2+ remodeling between ORAI1 and ORAI3." (PMID 31010205, 2019). "Orai3 overexpression in prostate cancer cells is able to impair the Orai1-mediated SOCE and causes prostate cancer cell resistance." (PMID 30884858, 2019). "It has been possible to establish the involvement of TRPV6 in SOCE in prostate cancer cells, as well as its physical association with ORAI1 via STIM1 and TRPC1 under the conditions of SOCE." (PMID 29671777, 2018). "Orai1 knockdown or ectopic expression of Orai1 dominant-negative mutants in prostate cancer cells downregulated SOCE activity and decreased susceptibility to diverse apoptosis-inducing stimuli including thapsigargin, tumor necrosis factor-α (TNF-α) and cisplatin." (PMID 31252656, 2019). "In some prostate cancers, disease progression seems to be associated with a switch from ORAI1-mediated Ca2+ influx to Ca2+ influx mediated by an ORAI1/ORAI3 heteromeric channel, due to genomic alterations in ORAI3 expression and/or tumor microenvironmental factors." (PMID 30754719, 2019). "Both STIM1 and ORAI1 were found to be overexpressed in both prostate cancer cell lines, while in PBMCs the expression of STIM1 and ORAI1 was very low or absent, implying that both biomarkers are specific for tumor cells in the bloodstream." (PMID 38903530, 2024). "We have also recently shown that overexpression of KDM2B in prostate cancer cells resulted in a significant upregulation of ORAI1 and Stim1 transcription." (PMID 38903530, 2024). "For example, ORAI1-ORAI3 heteromers induce apoptosis resistance in prostate cancer cells compared to ORAI1 monomers through reduced SOCE because the number of ORAI1 monomers is reduced." (PMID 38510751, 2024). "For instance, H2O2 reduces SOCE current in prostate cancer cell lines and human platelets, and increases mRNA expression of Orai1 and Stim1 in bovine brain capillary endothelial cells." (PMID 39606036, 2024). "The expression of STIM1 and ORAI1 in prostate cancer CTCs was examined by immunofluorescence using antibodies for CK, STIM1, and ORAI1." (PMID 38903530, 2024). "According to previous publications from our group and other research teams, STIM1 and ORAI1 are implicated in metastasis of prostate cancer, as it has been shown to promote invasion, migration, and EMT in prostate cancer cells." (PMID 38903530, 2024). "In prostate cancer biopsies, AA-mediated activation of Orai1/Orai3 channels enhanced intracellular Ca2+ concentration, which controls cell proliferation via Ca2+/CN-dependent activation of the transcription factor NFAT." (PMID 36612099, 2022). "On the other hand, Orai1 contributes to the establishment of an apoptosis-resistant phenotype in prostate cancer cells." (PMID 36310590, 2022). "Dubois and colleagues introduced a novel channel consisting of Orai1/Orai3 heterodimer and demonstrated its role in prostate cancer cell proliferation." (PMID 35821821, 2022). "Supportively, overexpression of Orai1 not only restored SOCE but also induced a similar rate of apoptosis in an aggressive type of prostate cancer cells compared to androgen-dependent cells." (PMID 36612099, 2022). "The androgen-independent stage of prostate cancer, which represents an aggressive phenotype, is manifested by downregulated Orai1 expression, which leads to apoptosis resistance." (PMID 36612099, 2022).